ZNF555 (zinc finger protein 555)
Description:
May be involved in transcriptional regulation.
Synonyms: MGC26707
Tractability: PROTAC: ubiquitination databases record sites on it.
Gene: Protein-coding gene on chromosome 19 (2,841,437 to 2,860,471, forward strand). Ensembl gene ENSG00000186300.
Subcellular location: Nucleus
Pathways (Reactome):
Gene expression (Transcription): Generic Transcription Pathway
Gene Ontology:
Molecular function: DNA-binding transcription activator activity, RNA polymerase II-specific; protein binding; DNA-binding transcription factor activity, RNA polymerase II-specific; RNA polymerase II transcription regulatory region sequence-specific DNA binding
Biological process: regulation of transcription by RNA polymerase II; positive regulation of transcription by RNA polymerase II; regulation of DNA-templated transcription
Cellular component: nucleus
Genetic constraint (gnomAD): Loss-of-function variants: 10 observed, 13.09 expected, observed/expected ratio (o/e) 0.76, 90% interval 0.47 to 1.29. The upper end of that interval is the gene's LOEUF score, 1.29, which puts it in group 5 of 6, group 1 being the genes least tolerant of losing a copy. Missense variants: 747 observed, 798.14 expected, observed/expected ratio (o/e) 0.94, 90% interval 0.88 to 0.99. Synonymous variants: 277 observed, 277.08 expected, observed/expected ratio (o/e) 1, 90% interval 0.9 to 1.1.
Homologues: Orthologues: chimpanzee ZNF555 (99% identical), macaque ZNF555 (97% identical), pig ZNF555 (84% identical), dog ZNF555 (81% identical), mouse Zfp78 (31% identical), Drosophila melanogaster CG3281 (20% identical), Drosophila melanogaster Phs (19% identical), Drosophila melanogaster CG2712 (18% identical). Paralogues in human: ZNF77 (43% identical), ZNF69 (41% identical), ZNF20 (40% identical), ZNF440 (37% identical), ZNF778 (37% identical), ZNF266 (37% identical), ZNF599 (37% identical), ZNF439 (36% identical), ZNF560 (36% identical), ZNF596 (35% identical), ZNF404 (35% identical), ZFP90 (35% identical), and 50 more.
Diseases named in the same sentence as ZNF555 in open-access papers:
ZNF555 is named in the same sentence as 5 diseases in open-access papers, as found by Europe PMC text mining. Sharing a sentence is not in itself a finding about the gene and the disease. The quoted sentences say what the papers report.
Ewing sarcoma (1 paper, 2024). A small round cell tumor that lacks morphologic, immunohistochemical, and electron microscopic evidence of neuroectodermal differentiation. "We therefore applied ZNF555 targeting first to rhabdomyosarcoma (RMS) and then to Ewing sarcoma cells, two mesenchymal cancers, which showed increased levels of ZNF555 expression." (PMID 39009887, 2024).
Facioscapulohumeral dystrophy (1 paper, 2024). Facioscapulohumeral muscular dystrophy (FSHD) is characterized by progressive muscle weakness with focal involvement of the facial, shoulder and limb muscles. "We have recently identified the uncharacterized ZNF555 protein as a component of a productive complex involved in the morbid function of the 4qA locus in facioscapulohumeral dystrophy." (PMID 39009887, 2024).
facioscapulohumeral muscular dystrophy (1 paper, 2024). An autosomal dominant disorder affecting the skeletal muscles of the face, scapula, and upper arm. "Recently, we identified the ZNF555 (Q8NEP9) protein as part of the productive transcriptional hub in myoblasts from patients with facioscapulohumeral muscular dystrophy (FSHD)." (PMID 39009887, 2024).
cancer (1 paper, 2024). A tumor composed of atypical neoplastic, often pleomorphic cells that invade other tissues. "Excitingly, the loss of ZNF555 results in cancer cell death." (PMID 39009887, 2024). "The cell death effect was further validated by targeting ZNF555 in the human cell-derived xenograft (CDX) mouse cancer model." (PMID 39009887, 2024). "Finally, the pan-cancer analysis of primary pediatric tumors illustrates the potential clinical relevance of ZNF555 targeting mesenchymal cancers and SOX2-related cancers." (PMID 39009887, 2024).
ZNF555 also shares sentences with these, for which no sentence is quoted: rhabdomyosarcoma (1 paper).